ACHE (acetylcholinesterase (Yt blood group))
Diseases named in the same sentence as ACHE in open-access papers (continued):
Sharing a sentence is not in itself a finding about the gene and the disease.
Sepsis (continued). "However, since sepsis can be classified into different phases it is conceivable that the increase or decrease in AChE-activity depends on the course of sepsis." (PMID 33203376, 2020). "In a CLP-induced sepsis model, the surviving mice showed a decrease in cholinergic neurons in the basal forebrain, a significant increase in AChE-activity and an increase in expression of their coding gene in the hippocampus and cortex, probably caused by microglial activation." (PMID 33203376, 2020). "Drugs could inhibit the inflammation, and/or oxidative stress is theoretically useful for maintaining diaphragmatic contractile function and AChE activity during sepsis." (PMID 32765805, 2020). "The primary objective of the present investigation was to evaluate the potential therapeutic effects of cholinesterase inhibitors on PMN functions during the early phase of sepsis and to investigate the roles of AChE and BChE as inflammatory markers in CLP-induced sepsis." (PMID 30804708, 2019). "Furthermore, the effects of antioxidant measurements on AChE activity during sepsis should be investigated in the future." (PMID 29230271, 2017). "We consider that oxidative stress might be responsible for decreased AChE activity in the diaphragms of rats induced with sepsis." (PMID 29230271, 2017). "In this study, we aimed to investigate whether the decreased AChE activity was related to oxidative stress by observing AChE activity in different grades of sepsis induced by caecal ligation and puncture (CLP)." (PMID 29230271, 2017). "Using low-grade and midgrade models of sepsis in rats, this study found that the AChE and CAT activities in the diaphragm decreased, while the contents of TBARS and protein carbonyls, the activity of MPO and SOD, and the SOD/CAT ratios increased at 24 h after CLP surgery." (PMID 29230271, 2017). "Sepsis represents a complex and multifaceted clinical condition, influenced by various patient-specific factors, which could contribute to the diverse dynamics of AChE activity observed in our study compared to previous reports." (PMID 37626609, 2023). "Moreover, the heterogeneity of sepsis and the presence of confounding factors, such as comorbidities and concomitant medications, might also influence AChE activity." (PMID 37626609, 2023). "Furthermore, the administration of multiple medications to sepsis patients may interfere with the cholinergic system, potentially affecting AChE activity." (PMID 37626609, 2023). "Additionally, the heterogeneous nature of sepsis and the presence of confounding factors, such as comorbidities and concomitant medications, could have influenced the observed AChE activity." (PMID 37626609, 2023). "Additionally, we aimed to assess whether changes in initially measured AChE activity could predict patient outcome following sepsis, considering its pivotal role as an enzyme responsible for modulation of cholinergic activity." (PMID 37626609, 2023). "However, AChE activity increased in the NRG group compared with the sepsis group (P < 0.01)." (PMID 32765805, 2020). "Additionally, the absence of correlation between AChE activity and disease severity scores or the length of ICU and hospital stay implies that AChE may not be directly linked to the severity of sepsis or predict the clinical course of the disease." (PMID 37626609, 2023). "Second, AChE activity at the NMJ of diaphragm is found to be significantly and negatively correlated with level of oxidative stress during sepsis." (PMID 29230271, 2017). "Inhibition of cerebral HMGB1 downregulated ChAT expression but resulted in increased expression of AchE, indicating that HMGB1 might be responsible for hyperactivation of the brain cholinergic system under sepsis." (PMID 34512319, 2021). "Moreover, our findings showed that AChE activity was not significantly increased in the acute phase of sepsis." (PMID 39370294, 2024).
Sepsis (continued). "We next tested whether the activity of AChE obtained from 32 patients surviving a 28-day period following sepsis onset differs from that of 11 patients who did not survive." (PMID 37626609, 2023). "In conclusion, our study suggests that the AChE assay may not be a suitable method for detecting the onset of sepsis." (PMID 37626609, 2023). "However, it is important to note that the current study design was not able to capture the potentially narrow time window of AChE-related changes in the cholinergic system following the onset of sepsis." (PMID 37626609, 2023). "Contrary to our initial hypothesis, we observed that AChE activity did not correlate with inflammatory biomarkers at the time of sepsis detection." (PMID 37626609, 2023). "Besides, AChE activity elevated after NRG-1β treatment as well, since our previous research suggested that oxidative stress played a vital role in AChE activity decrease in the diaphragm of rats with sepsis." (PMID 32765805, 2020). "Moreover, the mechanisms through which AChE activity was inhibited during sepsis were not clearly identified." (PMID 29230271, 2017). "However, the effects of different grades of sepsis on the activity of AChE were not illustrated in that study." (PMID 29230271, 2017). "AChE activity was found to be significantly and negatively correlated with the levels of TBARS and protein carbonyls, which indicated that oxidative stress may contribute to the decreased AChE activity during sepsis." (PMID 29230271, 2017). "However, the exact role of non-neuronal AChE activity in sepsis and its correlation with disease severity and patient outcomes remain unclear." (PMID 37626609, 2023).
respiratory failure (14 papers, 2012 to 2024). The significant impairment of gas exchange within the lungs resulting in hypoxia, hypercarbia, or both, to the extent that organ tissue perfusion is severely compromised. "Exposure to different toxicants causes inhibition in AChE activity which increases the neural junctions causing continuous nerve fiber or muscle stimulation causing many dangerous symptoms of respiratory failure, paralysis, and death." (PMID 39026256, 2024). "OP compounds inhibit acetylcholinesterase (AChE), causing an acute cholinergic crisis and respiratory failure through effects on the central, autonomic and peripheral nervous systems." (PMID 35147477, 2022). "In mammals, respiratory failure caused by inhibition of cerebral AChE is recognized as a cause of death." (PMID 33806197, 2021). "Organophosphates, such as parathion, malathion and chlorpyrifos, covalently inhibit acetylcholinesterase (AChE) and prevent the breakdown of the neurotransmitter acetylcholine, which can cause seizures, cardiovascular and respiratory failure, and death in humans at high doses of exposure." (PMID 35036170, 2021). "We have established a Gottingen minipig model of oral poisoning with 2.5 mL/kg of the 40% agricultural dimethoate emulsifiable concentrate formulation (EC40) which causes early respiratory failure, distributive shock, lethal cardiovascular collapse, and severe AChE inhibition." (PMID 31452424, 2020). "Organophosphorus (OP) agents and compounds are a diverse group of chemicals that potently inhibit acetylcholinesterase (AChE), a serine hydrolase, leading to cholinergic crisis and death by respiratory failure." (PMID 39553427, 2024). "We enrolled adults with respiratory failure and/or shock and measured plasma acetylcholinesterase (AChE) and butyrylcholinesterase (BChE) activity on days 1, 3, 5, and 7 after enrollment." (PMID 36474266, 2022). "In addition, red cell AChE assays showed that the respiratory failure and the initial distributive shock (both of which occurred within 30 min of ingestion) occurred before AChE activity had fallen by more than 70%." (PMID 22365945, 2012).
vascular dementia (14 papers, 2012 to 2024). A degenerative vascular disorder affecting the brain. "Hence, the combination of curcumin treatment with ACE inhibitors, especially perindopril for the inhibition of ACE and AChE activity in the brain is a better intervention in hypertensive patients with the risk of vascular dementia." (PMID 31739443, 2019). "Electroacupuncture treatment has been shown to reduce cytokine levels in the inflamed hippocampus, prolong the necrotic phase of pyramidal cells, and reduce acetylcholinesterase (AChE) activation in a rat model of vascular dementia." (PMID 37636433, 2023). "EA treatment reduced inflammatory cytokines in the hippocampus, prolonged the necrosis period in pyramidal cells, and decreased activation of Acetylcholine Esterase(AChE) at vascular dementia rats." (PMID 30621676, 2019). "AChE activity was significantly increased in hippocampus in L-methionine induced model of vascular dementia and the activity of AChE depends largely on the membrane characteristics, since the enzyme is membrane bound." (PMID 25050360, 2014). "Furthermore, inhibition of AChE by donepezil or GAL increased proliferating cells or hippocampal neurogenesis in the dentate gyrus of vascular dementia rats or normal mice." (PMID 31046739, 2019). "Furthermore, AChE inhibitors, such as donepezil hydrochloride, have been shown to enhance neurogenesis via downregulation of AChE activity in mice with vascular dementia." (PMID 27809818, 2016). "In addition, the enhanced density of Bcl-2-immunopositive neurons and the suppression of AChE in the area just mentioned were also observed in accompany with the increased spatial memory in animal model of vascular dementia." (PMID 22952555, 2012). "For example, both AChE activity and ACh content were decreased in rat BCCAO model of vascular dementia in this study." (PMID 26818681, 2016).
Constipation (13 papers, 2013 to 2025). Infrequent or difficult evacuation of feces. "To investigate the mechanism of action of SPA on the cholinergic regulation for gastrointestinal mobility, we assessed the AChE activity by measuring the AChR M3 downstream signaling pathway in the airway tissue of the Lop-induced constipation model." (PMID 30795644, 2019). "For example, some studies have shown that AChE activity is reduced in the intestines of patients with constipation, which may be related to the pathophysiological mechanism of constipation." (PMID 40002098, 2025). "Furthermore, a decrease in AChE activity was detected in the colon tissue of Lop-induced constipation rats and serum of activated carbon-induced constipation mice." (PMID 36548335, 2022). "In addition, the AChE activity was statistically significantly lower in the colon tissue of Lop-induced constipation rats and the serum of activated carbon-induced constipation mice than their untreated counterparts." (PMID 35743302, 2022). "Changes in AChE activity in patients with constipation may affect intestinal motility." (PMID 40002098, 2025). "Moreover, 72-SDC could also raise Ghrelin, ET-1, VIP and AchE serum levels in constipation mice." (PMID 30832248, 2019). "Compared with patients with constipation, MTL, Gas, ET, AChE, SP and VIP levels in the serum of healthy individuals are higher whilst the levels of SS are lower." (PMID 25452815, 2015). "Effect of various samples on serum MTL (motilin), Gas (gastrin), ET (endothelin), SS (somatostatin), AchE (acetylcholine enzyme), SP (substance P) and VIP (vasoactive intestinal peptide) levels in activated carbon-induced constipation model mice." (PMID 25464378, 2014). "The serum levels of MTL, Gas, ET, AChE, SP and VIP in patients with constipation are lower than those in healthy individuals while the SS levels are higher." (PMID 23935751, 2013).
epilepsy (13 papers, 2015 to 2025). A brain disorder characterized by episodes of abnormally increased neuronal discharge resulting in transient episodes of sensory or motor neurological dysfunction, or psychic dysfunction. "A role for reversible AChE inhibitors in the treatment of epilepsy has focused largely on seizures that are caused by exposure to organophosphates (e.g., soman) that bind irreversibly to AChE." (PMID 27799911, 2016). "Previous studies have shown that reducing AChE activity not only improves cognitive performance but also stabilizes neuronal excitability, thereby offering neuroprotective effects in epilepsy." (PMID 39911825, 2024). "A-1 had shown significantly higher antioxidant activity as well as AChE inhibitory activity and stronger interaction with proteins involved in epilepsy and other neurodegenerative disorders, especially AChE enzyme." (PMID 36765125, 2023). "The role of cholinergic neurotransmission and acetylcholinesterase (AChE) in epilepsy is well known." (PMID 25653736, 2015). "The increase in the activity of AChE in epilepsy is well documented." (PMID 33670383, 2021). "Studies have shown that AChE may be an important therapeutic target for adjunct treatment in epilepsy as numerous AChE-inhibitors were tested in experimental settings for this purpose as a memory enhancer." (PMID 34422216, 2021). "Further support to the notion that the cholinergic system is crucially implicated in SHE is given by the observation that a recessive form of the epilepsy is associated with mutant proline-rich membrane anchor 1 (PRIMA1), which anchors acetylcholinesterase (AChE) to the synaptic membrane." (PMID 33255633, 2020). "Further studies will be required to assess the relationship between AChE inhibitors like propoxur and exposure during development that could provide a new etiology for reflex seizures/epilepsy." (PMID 31546644, 2019).
delirium (12 papers, 2015 to 2025). A disorder characterized by confusion; inattentiveness; disorientation; illusions; hallucinations; agitation; and in some instances autonomic nervous system overactivity. "Increased AChE activity, potentially indicating low acetylcholine availability in the synapses, has been associated with increased risk of postoperative delirium and with major neurocognitive disorder." (PMID 36474266, 2022). "Increased AChE activity has been associated with increased risk of postoperative delirium and with major neurocognitive disorder." (PMID 36474266, 2022). "Increased and decreased levels of AChE activity have been associated with an increased risk of postoperative delirium (POD) and delirium during critical illness, while decreased levels of BChE have been associated with increased inflammatory processes and also an increased risk of POD." (PMID 39715945, 2024). "AChE-activity is therefore suitable for differentiating SAE from other causes of delirium." (PMID 33203376, 2020). "Therefore, AChE activity was suitable for differentiating SAE from other causes of delirium." (PMID 37629287, 2023). "Previous research on AChE and BChE activities has mainly focused on perioperative settings, examining their potential as biomarkers of delirium." (PMID 39715945, 2024). "Patients with AChE activity at the 75th percentile, for example, would have on average a 64% increased odds of developing delirium compared to those with values at the 25th percentile." (PMID 36474266, 2022). "Molecules identified for this criterion from the RNAseq dataset with a known or possible involvement in encephalopathy and delirium included miR-320a-3p, ACHE, TSPO, and TIMP1, which interacted with MMP9." (PMID 34573990, 2021). "Due to recent studies which supposed an important role of AChE and BChE in delirium of critically ill patients this study focused on AChE and BChE in patients after cardiac surgery and its impact on postoperative delirium." (PMID 28560042, 2017). "The initial massive enhanced AChE activity and the delirium and other organ failures represent a complex of pathophysiological symptoms." (PMID 26550498, 2015). "Therefore, in contrast to single measurements longitudinal measurement of AChE-activity in septic patients with delirium is able to diagnose SAE." (PMID 33203376, 2020). "In addition, it should be considered that different variables, such as sex, AchE inhibitor therapy, delirium, and stress, can affect AchE activity." (PMID 31191751, 2019). "We tested the hypothesis that AChE and BChE have an impact on patients after cardiac surgery with postoperative delirium." (PMID 28560042, 2017). "In summary, measuring the AChE activity in ICU patients with indistinct hypoactive delirium and organ dysfunction could be a proper option in the therapeutic concept." (PMID 26550498, 2015). "In contrast, no change in AChE activity was observed in nonseptic patients, even those experiencing delirium." (PMID 39715945, 2024). "AChE activities tends to decrease postoperatively in patients with delirium more, but remain stable in patients without delirium, while BChE activities decrease postoperatively in both, patients with and without delirium." (PMID 36894596, 2023). "In contrast, in non-septic patients with delirium or cognitive dysfunction no statistically significant change in AChE-activity could be detected during the observation period." (PMID 33203376, 2020). "Moreover, it was of interest to what extent AChE-activity in septic patients with pronounced “inflammatory load” differs from non-septic, critically-ill patients with and without delirium." (PMID 33203376, 2020).
hepatocellular carcinoma (10 papers, 2012 to 2025). A malignant tumor that arises from hepatocytes. "In contrast, host gene-associated antisense RNAs can also silence paired protein-coding genes, as exemplified by the acetylcholinesterase (AChE) gene, which is silenced by AChE-AS lncRNA in hepatocellular carcinoma through triggering of histone methylation." (PMID 31572684, 2019). "So far, the study of AChE in pathological liver has been restricted to hepatocellular carcinoma or to animal models that have less BChE than AChE activity." (PMID 23028565, 2012). "The roles and implications of (AChE) in hepatocellular carcinoma HCC remain elusive." (PMID 38429330, 2024). "Interestingly, AChE has been proposed as a key predictor for hepatocellular carcinoma prognosis." (PMID 23028565, 2012). "Similarly, in later years, it was demonstrated that in hepatocellular carcinoma (HCC), AChE activated the STAT3 and AKT pathways by interacting with the androgen receptor (AR), enhancing the migration and invasion of HCC cells while inhibiting their apoptosis." (PMID 40678419, 2025).
ischemic stroke (10 papers, 2015 to 2025). A stroke disorder caused by obstruction of blood flow to the brain, due to thrombotic (local blood clot formation) or embolic (due to a blood clot or other material traveling from another site) event. "Low blood AChE and cholinergic state activity increase cardiac and ischemic stroke mortality, thereby increasing the risk of major adverse cardiovascular events." (PMID 37873057, 2023). "Male ischemic stroke patients had higher levels of neuronal AChE compared to healthy controls (p = 0.0006)." (PMID 40950018, 2025). "In a preclinical study of ischemic stroke, Nevirapine administration offered neuroprotective effects by reducing hippocampal levels of acetylcholinesterase (AChE) and glutamate following MCAO in rats." (PMID 36425574, 2022). "Consistently, miR-124 was predicted to suppress acetylcholinesterase (AChE; Nadorp and Soreq, 2014), whose plasma level was reduced in patients post ischemic stroke, indicating a physiological relevance between miR-124 and AChE." (PMID 26041995, 2015). "Moreover, our results also reveal that ischemic stroke increases AChE activity, which corresponds with the results of a previous study." (PMID 39683536, 2024). "Male ischemic stroke patients had elevated MTHFR and AChE levels compared to healthy controls." (PMID 40950018, 2025). "In the present study, we demonstrate the relationship of microglial activation and AChE activity using TSPO and AChE targeting positron emission tomography (PET) radioligands, and manipulating respective activities with inhibitors, in the ischemic stroke rat model." (PMID 34072449, 2021).